GPR141 (G protein-coupled receptor 141)
Diseases named in the same sentence as GPR141 in open-access papers:
GPR141 is named in the same sentence as 34 diseases in open-access papers, as found by Europe PMC text mining. Sharing a sentence is not in itself a finding about the gene and the disease. The quoted sentences say what the papers report.
breast carcinoma (3 papers, 2023 to 2025). "GPR141 mutations and their significance in cancer need to be explored, which will provide a cutting-edge and successful therapeutic strategy beyond breast cancer too." (PMID 37204251, 2023). "Through both in vivo and in vitro experiments, this study demonstrated that upregulated expression of GPR141 enhances the migratory behavior of breast cancer cells." (PMID 40959105, 2025). "GPR141 amplification was observed in different breast cancer sub-types, with high alteration frequency observed in breast invasive mixed mucinous carcinoma (4% altered out of 25 cases) and breast invasive ductal carcinoma (2.23% in 1660 cases)." (PMID 37204251, 2023). "We identify aberrant expression of G-protein-coupled receptor 141 (GPR141) in different breast cancer subtypes that correlate with poor prognosis." (PMID 37204251, 2023). "By employing p-mTOR1 inhibitor rapamycin in breast cancer cells, we established the p-mTOR1 transduction pathways’ relevance in GPR141-mediated carcinogenesis." (PMID 37204251, 2023). "Our findings describe the role of GPR141 in breast cancer proliferation, and metastasis, as well as in influencing the tumor microenvironment." (PMID 37204251, 2023). "To determine the proliferative and migratory pattern in breast cancer cells, we performed siRNA-mediated knockdown of GPR141 in ZR-75-1 cells." (PMID 37204251, 2023). "This research uncovers GPR141 as a stimulator of breast tumorigenesis and metastasis, making it a candidate target for breast cancer therapeutics." (PMID 37204251, 2023). "To determine the status of GPR141 in breast carcinoma, we assessed the expression levels of GPR141 in different breast cancer and healthy breast cell lines with western blot data and measured transcript levels of GPR141 in these cells." (PMID 37204251, 2023). "For example, the roles of G-protein-coupled receptor 141 (GPR141) in breast cancer proliferation and metastasis have been elucidated, suggesting that targeting this receptor could offer new avenues for treatment." (PMID 40075655, 2025). "Modulating GPR141 expression could pave the way for a better therapeutic approach to regulating breast cancer progression and metastasis." (PMID 37204251, 2023). "In concordance with cancer progression, tumor sections also showed higher expression of proliferation marker, Ki67, and lower expression of E-cadherin on GPR141 transfected tumors compared to control tumors, confirming its involvement in GPR141-mediated breast cancer progression." (PMID 37204251, 2023). "Moreover, the knockdown of GPR141 deters cellular proliferation and migration, G1 stage cell cycle arrest, in breast cancer cells." (PMID 37204251, 2023). "Furthermore, GPR141 promotes breast tumor development in vivo and influences the tumor milieu to facilitate breast cancer progression." (PMID 37204251, 2023). "GPR141 silencing impedes the migration of breast cancer cells." (PMID 37204251, 2023). "Our study indicates that GPR141 and its regulated signaling circuitry could be a promising therapeutic candidate for controlling breast cancer development and metastasis." (PMID 37204251, 2023). "However, the molecular mechanism via which GPR141 advances breast cancer remains elusive." (PMID 37204251, 2023).
breast carcinoma (continued). "However, the potential role of GPR141 in cancers beyond breast cancer remains unvalidated, and no study has yet predicted or analyzed the function of GPR141 across pan-cancer contexts." (PMID 40959105, 2025). "However, the role of GPR141 in the assessment of patient health outcomes in breast cancer is still lacking." (PMID 37204251, 2023).
Breast invasive carcinoma (2 papers, 2023 to 2025). "cBioPortal downloaded from TCGA datasets of 1084 invasive breast carcinoma patient samples estimated a positive correlation of mRNA expression of mTOR with GPR141 mRNA expression level (Spearman’s correlation = 0.210, P = 2.70e-12)." (PMID 37204251, 2023).
breast tumor (1 paper, 2023).
head and neck cancer (1 paper, 2023). A primary or metastatic malignant neoplasm affecting the head and neck. "TCGA database shows enhanced expression of GPR141 in leukemia, ovarian cancer, and head and neck cancer." (PMID 37204251, 2023).
hepatocellular carcinoma (1 paper, 2025). A malignant tumor that arises from hepatocytes. "Immunohistochemical analysis demonstrated significantly elevated GPR141 expression in both lung adenocarcinoma and hepatocellular carcinoma tissues compared with their normal counterparts, which aligned with our preliminary bioinformatic predictions." (PMID 40959105, 2025). "Immunohistochemical results showed that the expression of GPR141 in lung adenocarcinoma and hepatocellular carcinoma was higher than that in adjacent tissues." (PMID 40959105, 2025). "To address this knowledge gap, we performed immunohistochemical analysis using clinically obtained lung adenocarcinoma (LUAD) and hepatocellular carcinoma (HCC) samples to comparatively evaluate GPR141 expression patterns between normal and tumor tissues." (PMID 40959105, 2025). "We observed that in both lung adenocarcinoma (LUAD) and hepatocellular carcinoma (HCC), GPR141 exhibits predominantly cytoplasmic localization." (PMID 40959105, 2025). "Finally, the immunohistochemical findings conclusively confirmed elevated GPR141 expression in clinical specimens of lung adenocarcinoma (LUAD) and hepatocellular carcinoma (HCC) compared to adjacent normal tissues." (PMID 40959105, 2025).
herpes zoster (1 paper, 2024). A common dermal and neurologic disorder caused by reactivation of the varicella-zoster virus that has remained dormant within dorsal root ganglia, often for decades, after the patient's initial exposure to the virus in the form of varicella (chickenpox). "A genetic variant of GPR141 is linked to an accelerated onset of herpes zoster in patients with rheumatoid arthritis and psoriasis undergoing treatment with the JAK inhibitor tofacitinib, a JAK inhibitor also used in the treatment of UC." (PMID 39165421, 2024).
lung adenocarcinoma (1 paper, 2025). A carcinoma that arises from the lung and is characterized by the presence of malignant glandular epithelial cells. "We detected the protein expression of GPR141 in normal lung epithelial cells and lung adenocarcinoma cells." (PMID 40959105, 2025). "And we stably knocked down GPR141 in lung adenocarcinoma cell lines A549 and H1975, and the changes of cell proliferation, migration and invasion were detected by CCK8, Transwell migration and invasion experiments." (PMID 40959105, 2025). "To explore the physiological role of GPR141 in cancer, we established stable GPR141 knockdown in lung adenocarcinoma cell lines A549 and H1975." (PMID 40959105, 2025). "And the result showed that the expression of GPR141 in lung adenocarcinoma cells was higher than that in normal lung epithelial cells." (PMID 40959105, 2025). "After knocking down GPR141 in A549 and H1975, we found that the proliferation, migration and invasion of lung adenocarcinoma cells decreased after knocking down GPR141." (PMID 40959105, 2025).
metastatic tumors (1 paper, 2025). "Additionally, we observed that GPR141 expression was significantly higher in metastatic tumors than in primary tumors in SKCM." (PMID 40959105, 2025).
multiple sclerosis (1 paper, 2025). A progressive autoimmune disorder affecting the central nervous system resulting in demyelination. "At the same time, in multiple sclerosis, when GPR141 is missing, it will damage the immune regulation pathway, which in turn increases the severity of multiple sclerosis." (PMID 40959105, 2025).
RASopathy (1 paper, 2017). Developmental syndromes caused by germline mutations (or in rare cases by somatic mosaicism) in genes that alter the Ras subfamily and mitogen-activated protein kinases that control signal transduction. "One top region overlapped between these independent approaches, and we showed dysregulation of a gene in this region, GPR141, in a RASopathy neural cell line." (PMID 28076348, 2017). "A gene in this region, GPR141, demonstrates reproducibly reduced expression in RASopathy neural cell lines." (PMID 28076348, 2017).
triple-negative breast carcinoma (1 paper, 2023). An invasive breast carcinoma which is negative for expression of estrogen receptor (ER), progesterone receptor (PR), and human epidermal growth factor receptor 2 (HER2). "To ascertain GPR141’s potential contribution to in vitro breast carcinogenesis, we overexpressed GPR141 in Estrogen receptor positive (MCF-7) and triple-negative breast cancer cells (MDA-MB-231)." (PMID 37204251, 2023).
cancer (2 papers, 2023 to 2025). A tumor composed of atypical neoplastic, often pleomorphic cells that invade other tissues. "The findings demonstrate that GPR141 exhibits considerable diagnostic potential across different cancer types." (PMID 40959105, 2025). "Recent studies have shown that two articles concerning the association between GPR141 and cancer in PubMed." (PMID 40959105, 2025). "Our findings demonstrated statistically significant associations between GPR141 expression levels and immune cell infiltration patterns, particularly involving cancer-associated fibroblasts (CAFs) and endothelial cells (ECs) in specific tumor types." (PMID 40959105, 2025). "The results showed that GPR141 expression was positively correlated with the infiltration of cancer-associated fibroblasts in BLCA, BRCA (BRCA LumA), COAD, ESCA, HNC-HPV (-), LUAD, LUSC, PAAD, STAD and THYM." (PMID 40959105, 2025). "Furthermore, functional enrichment analyses provided insights into the biological processes and signaling networks associated with GPR141 in cancer development and progression." (PMID 40959105, 2025). "Additionally, significant associations between GPR141 expression and immune subtypes were observed in 15 cancers." (PMID 40959105, 2025). "Furthermore, comprehensive pan-cancer analysis indicated that GPR141 expression exhibited substantial associations with numerous chemokine family members, excluding CCL1, CCL16, and CCL27." (PMID 40959105, 2025). "In addition, our investigation identified significant associations between elevated GPR141 expression levels and increased endothelial cell infiltration across several cancer types, including COAD, HNSC-HPV (-), LGG, LUSC, PAAD, PRAD, READ, and STAD." (PMID 40959105, 2025). "In this study, we used the data of TCGA database and a variety of bioinformatic websites to analyze and predict the expression and related functions of GPR141 in pan-cancer 39-47." (PMID 40959105, 2025). "This investigation employed comprehensive bioinformatics approaches to systematically analyze GPR141 across multiple cancer types, focusing on its expression patterns, prognostic significance, genomic variations, and immunological associations." (PMID 40959105, 2025). "Gene enrichment analysis showed that GPR141 was mainly involved in immune-related pathways in pan-cancer." (PMID 40959105, 2025). "We performed correlation analysis of these six genes (PTPRC, TLR8, PLEK, NCKAP1L, RGS18 and CLEC12A) with GPR141 in pan-cancer." (PMID 40959105, 2025). "The results showed that PTPRC, TLR8, PLEK, NCKAP1L, RGS18 and CLEC12A displayed strong correlation with GPR141 in most cancer types." (PMID 40959105, 2025). "To explore the potential prognosis value of GPR141, we investigated the correlation between GPR141 expression and prognosis of the patients with different cancers by using GEPIA2.0." (PMID 40959105, 2025). "Through multidimensional analysis, this research provides novel insights into the multifaceted roles of GPR141 in cancer biology, offering a more comprehensive understanding of its involvement in tumor development and progression." (PMID 40959105, 2025). "Next, we found that high expression of GPR141 was associated with longer overall survival in HNSC, MESO, SARC and SKCM cancers." (PMID 40959105, 2025). "This comprehensive pan-cancer analysis aimed to elucidate the potential immunoregulatory role of GPR141 in the tumor microenvironment." (PMID 40959105, 2025). "We investigated GPR141 expression patterns across molecular and immune subtypes in pan-cancer using TISIDB database data." (PMID 40959105, 2025).
cancer (continued). "However, as a member of the G protein-coupled receptor family, the function of GPR141 is still unclear, and its function in pan-cancer is even less known." (PMID 40959105, 2025). "Regarding major histocompatibility complex (MHC) molecules, the expression profile of GPR141 demonstrated predominantly positive correlations with most MHC components across multiple cancer types, with only a minority of MHC molecules exhibiting a negative correlation." (PMID 40959105, 2025). "These collective results indicate that GPR141 may serve as a promising therapeutic target for immunotherapeutic interventions, potentially improving clinical outcomes in cancer patients." (PMID 40959105, 2025). "For comprehensive analysis of GPR141 genomic alterations across various malignancies, we conducted a systematic investigation utilizing the cBioPortal bioinformatics resource, which integrates and processes cancer genomics data from The Cancer Genome Atlas (TCGA) database." (PMID 40959105, 2025). "In pan-cancer, the expression levels of PTPRC, TLRB, PLEK, NCKAP1L, PGS18 and CLEC12A were positively correlated with GPR141." (PMID 40959105, 2025). "Furthermore, we identified significant correlations between GPR141 expression levels and specific molecular/immune subtypes across cancers, suggesting that targeting these distinct subtypes could provide deeper insights into GPR141's functional roles in tumor biology." (PMID 40959105, 2025). "To elucidate the biological functions of GPR141 in cancer development, we employed GEPIA2.0 to identify 100 genes demonstrating the highest co-expression correlation with GPR141 across TCGA malignancies." (PMID 40959105, 2025).
tumor (2 papers, 2023 to 2025). "Functional characterization revealed that GPR141 knockdown significantly suppressed tumor cell proliferation, migration, and invasive capacities." (PMID 40959105, 2025). "In the present investigation, we systematically evaluated the immunomodulatory role of GPR141 through comprehensive analysis of tumor microenvironment characteristics." (PMID 40959105, 2025). "GPR141 is closely related to the prognosis, genetic changes and immune infiltrating cells of tumor patients." (PMID 40959105, 2025). "Through comprehensive analysis utilizing the GEPIA2.0, we systematically identified multiple genes exhibiting co-expression patterns with GPR141 across diverse tumor types and normal tissues." (PMID 40959105, 2025). "To investigate the function of GPR141 in tumor development in vivo, we administered control pCMV3 and GPR141 overexpressed MDA-MB-231 cells orthotopically into the mammary fat pad of female NOD SCID mice." (PMID 37204251, 2023). "Additionally, our investigation demonstrated that the majority of chemokine receptors displayed positive regulatory relationships with GPR141 expression patterns in most analyzed tumor types." (PMID 40959105, 2025). "We also showed tumor development in GPR141 overexpressed cells by the Chick CAM model." (PMID 37204251, 2023). "Mice showed pronounced tumor growth in GPR141 overexpressed cells compared to the control cells." (PMID 37204251, 2023). "Our results show that GPR141 facilitates migration and influences the tumor microenvironment." (PMID 37204251, 2023). "However, understanding the role of GPR141 in the crosstalk between tumor cells and their niche can be an intriguing treatment strategy to address multiple mechanism driving tumorigenesis." (PMID 37204251, 2023). "Furthermore, we have shown enhanced tumor development in GPR141 overexpressed cells." (PMID 37204251, 2023). "Altogether, these research findings elucidated that GPR141 accelerates breast carcinogenesis by modulating EMT transition and tumor niche." (PMID 37204251, 2023).
GPR141 also shares sentences with these, for which no sentence is quoted: periodontitis (2 papers); Alzheimer disease (1); breast invasive ductal carcinoma (1); colon adenocarcinoma (1); COVID-19 (1); Esophageal carcinoma (1); Fuchs' dystrophy (1); Glioblastoma multiforme (1); glioma (1); head and neck squamous cell carcinoma (1); inflammatory breast carcinoma (1); leukemia (1); lung carcinoma (1); Lung squamous cell carcinoma (1); ovarian carcinoma (1); pancreatic adenocarcinoma (1); psoriasis (1); rectum adenocarcinoma (1); rheumatoid arthritis (1); Stomach adenocarcinoma (1); uterine corpus endometrial carcinoma (1).